PLAUR (plasminogen activator, urokinase receptor)
Diseases named in the same sentence as PLAUR in open-access papers (continued):
Sharing a sentence is not in itself a finding about the gene and the disease.
cancer (continued). "In the research field of regulation of cancer cell invasion and metastasis, MIF showed similar effect or intersection with hypoxia, such as association with an increased expression of MMPs and PLAUR and macrophage recruitment." (PMID 36703790, 2022). "PLAUR belongs to the plasminogen activation system and is widely involved in various cancer-specific processes, including inflammation- and immune- and hypoxia-related pathways." (PMID 36035192, 2022). "The urokinase-type plasminogen activator receptor (PLAUR) plays a critical role in the initiation and progression of several cancers, including KIRC." (PMID 36052236, 2022). "CCLE was used to assess the expression distribution of EME1/HNRNPAB/PLAUR/SEMA3A in pan-cancer cell lines." (PMID 36091160, 2022). "In the present study, we first explored the expression profile and prognostic values of PLAUR in pan-cancer based on The Cancer Genome Atlas and Genotype-Tissue Expression databases." (PMID 36052236, 2022). "KEGG pathway analysis suggests that PLAU and PLAUR are mainly involved in the proteoglycan-related cancer signaling pathway, Wnt signaling pathway, and TNF signaling pathway." (PMID 35087738, 2021). "Consistently, our results showed that PLAUR was considered as a cancer therapeutic target and high expression of PLAUR can predicted poor OS in OSCC patients." (PMID 33892811, 2021). "Only AURKA, BIRC5, and PLAUR were served as the chemotherapy targets for cancer treatment currently." (PMID 33892811, 2021). "It was shown to aid the invasion and metastasis of various types of cancer cells via binding to PLAUR, subsequently activating downstream pathways like ERK1/2 and PI3K/Akt." (PMID 30323894, 2018). "An antibody that showed beneficial anti-cancer effects in preclinical studies was shown to interfere with interaction of PLAUR and integrins." (PMID 29254187, 2017). "To further decipher transcriptional effects of PLAUR in cancer cells, we have performed a microarray study." (PMID 29254187, 2017). "The role of urokinase plasminogen activator receptor (PLAUR) in cancer has been extensively studied and as per our knowledge, there is no data available which documents changes in the transcriptome of PLAUR silenced (PLAURsi) cells." (PMID 29254187, 2017). "Previously it was thought that PLAUR promotes cancer progression by regulation of extracellular proteolysis on the cell surface, but recent studies show that PLAUR is involved in many intracellular mechanisms promoting cell survival." (PMID 29254187, 2017). "PLAUR is highly expressed in majority of cancers and high PLAUR expression correlates with poor patient survival and bad prognosis." (PMID 29254187, 2017). "Our data contribute to the understanding of the role of PLAUR in cancer and provide a rationale for addressing the correlation between PLAUR and TLR4 status, and DNA repair/CHK1 inhibitors efficiency." (PMID 27685627, 2016). "Since CTCs have been reported recently as precursors and contribute significantly to BC metastasis, high HER2 and PLAUR co-amplification can be expected to be seen only during the later stages of malignant tumor development (CTCs to distant metastases stage)." (PMID 25897424, 2015). "KEGG analysis demonstrated that the PLAUR gene was involved in the proteoglycans in cancer." (PMID 40535127, 2025). "PLAUR promotes neutrophil activation and degranulation while expressed on neutrophils, and also assists neutrophil infiltration to the inflammatory sites while expressed on cancer cells." (PMID 38396677, 2024). "Endocytic regulation of PLAU/PLAUR may serve to regulate a cell’s migration and invasion capacity and has been implicated in functions including EMT in several cancer types." (PMID 36674745, 2023).
cancer (continued). "Furthermore, PLAUR is found to be involved in the mechanisms related to the invasion of malignant germ cells and is upregulated in cancer cases." (PMID 35774118, 2022). "PLAUR plays a crucial role in the initiation and progression of various cancers, including KIRC." (PMID 36052236, 2022). "In recent years, many studies have shown that PLAUR can be an effective prognostic biomarker and potential therapeutic target for GC due to the fact that the suppression of PLAUR could sensitize cancer cell death by inducing DNA damages." (PMID 34354996, 2021). "Therefore, we first interrogated the publicly available RNA-Sequencing datasets of The Cancer Genome Atlas (TCGA) and found that PLAUR expression is elevated in breast and many other common cancers when compared with their respective control tissues." (PMID 32337090, 2020). "Transcription factors such as Sp1, NF-κB, TCF, and hypoxia-inducible factor 1α, that are frequently activated by different types of cancer-related signaling pathways, binds to the cis-acting elements located upstream of the PLAUR gene to trigger its elevated expression in cancer." (PMID 29484286, 2018). "Hence, decreased RRM2B expression in PLAURsi cells can negatively regulate survival of cancer cells and provide a strong link of PLAUR to kidney damage pathways." (PMID 29254187, 2017). "In addition, catalytically inactive PLAU also promotes cell migration via binding to PLAUR and initiation of intracellular signaling mediated by integrins; along with other PLAUR co-receptors in cancer cells, neutrophils, endothelial and smooth muscle cells." (PMID 29254187, 2017). "We found six genes, ADIPOQ, DKK1, IGF1, IGF1R, IGF2, and PLAUR were shared by all the four cancers." (PMID 28676692, 2017). "We show that PLAUR actively promotes DNA repair in cancer cells." (PMID 27685627, 2016). "On the other hand, taking into account the molecules involved in cell to cell signaling events, the most DEG was osteopontin (SPP1), which has been found disregulated in several subtypes of cancer which in turn is linked to PLAU and PLAUR, also highly overexpressed." (PMID 25887408, 2015). "In addition to PLAUR and LAMB3, S100A10 was another gene upregulated by both hypoxia and hypoglycaemia based on our array analysis, and has been shown to be important in cancer cell invasion and metastasis through colocalization with uPA/PLAUR system." (PMID 25079072, 2014). "Studies suggest that tissue-expressed PLAUR may be a biomarker for cancer progression." (PMID 40561678, 2025). "Highly-expressed coagulation fibrinolysis genes, including PLAU, PLAUR, and SERPINE1, are associated with monocytic infiltration and overexpressed immune checkpoints (PD-L2 and CD276/B7-H3) in pan-cancer, indicating that increased PLAU may be related to the TME in cancer." (PMID 38025757, 2023). "Indeed, limma analysis of differentially expressed genes indicated an increased expression of four genes related to cancer stemness: the pluripotency factor KLF4, the PLAUR gene encoding for the urokinase plasminogen activator surface receptor (uPAR), CD44 and CD166." (PMID 36077264, 2022). "Therefore, we propose that MRP-7-mediated upregulation of PLAUR may facilitate paclitaxel resistance and cancer stem cell-like features of EC by activating the WNT signaling pathway." (PMID 34950596, 2021). "Downregulation of PLAUR could inhibit cancer proliferation and metastasis in several cancers." (PMID 33892811, 2021). "Our results support a TNBC model whereby in older cohorts, myeloid cells and CAFs interact with cancer basal cells via LGALS9/P4HB, PPIA/BSG and PLAU/PLAUR signaling to promote EMT and cell motility." (PMID 41188599, 2025). "Additionally, given the strong correlation between PLAUR expression and immune cell infiltration, as well as immune checkpoints, developing PLAUR-targeted immunotherapies could enhance the efficacy of existing cancer treatments." (PMID 40561678, 2025).
cancer (continued). "Eight proteins (A4GALT, ASIP, CTSF, MARE1, PDXK, SEM4A, PLAUR, VARS1) were observed to have evidence of multi-trait colocalization between the index protein, intermediate phenotypes, and the index cancer endpoint, which may serve to elucidate aetiological pathways to cancer risk." (PMID 38684708, 2024). "The KEGG pathway describes a typical PLAUR-mediated cell–ECM interaction with “Focal adhesion”, “Complement and coagulation cascades”, and “Proteoglycans in cancer." (PMID 38396677, 2024). "Therefore, presence of alternatively spliced PLAUR mRNA isoforms in cancer tissue and their potential impact on survival should be accounted for as they may also contribute to discrepant results on prognostic utility of uPAR antigen or PLAUR mRNA between cancer types." (PMID 36124441, 2023). "Considering that TCGA database lacks normal tissue data for some cancers, we then utilized the GEPIA database (including TCGA and GTEx databases) to verify further the differences in the expression of PLAUR in these 20 cancers." (PMID 36052236, 2022). "The enrichment analysis revealed that most pathways enriched by PLAUR- and SEMA3A-related genes were duplicated, suggesting that these two genes are involved in the same pathways leading to cancer development." (PMID 36091160, 2022). "In this study, we first analyzed the expression of PLAUR in pan-cancer using data from TCGA database, after which we used the GEPIA database to confirm the expression and prognostic potential of PLAUR." (PMID 36052236, 2022). "In OSCC, on average, cancer cells expressed high mRNA levels of F3, PLAU and PLAT, but little if any of PLAUR, F2R or SERPINE1." (PMID 35053621, 2022). "The results also confirmed that most pathways enriched by PLAUR- and SEMA3A-related genes were duplicated, suggesting that these two genes are involved in the same pathways leading to cancer development." (PMID 36091160, 2022). "These genes are PLAUR, UCN, PABPC1L, SLC16A12, NFE2L3, and KCNAB1, and some of them have been previously reported in multiple types of cancer." (PMID 35211477, 2021). "We have recently demonstrated that silencing PLAUR affects phosphorylation of RAD51 and impairs HR pathway in cancer cells." (PMID 29254187, 2017). "These genes belong to relevant intracellular signaling pathways in cancer such as PI3K-Akt (COL4A2, MYC, PDGFA, SPP1), proteoglycans (HIF1A, MYC, PLAUR, TGFB1), and Hippo (CTGF, MYC, NF2, TGFB1)." (PMID 29075357, 2017). "Expression of miR-204 was significantly down-regulated in cancer and OSMF tissues, while expression of its three target genes (MMP9, PLAUR and SERPINE1) showed significant up-regulation in cancer only." (PMID 27597234, 2016). "Moreover, LAMP1 expression strongly correlated with p21 in cancer tissue (R = 0.95) and with the surface senescence marker PLAUR (uPAR), which has also been reported as a SEN surface marker and target for senolytic immunotherapy." (PMID 40545776, 2025). "The analysis of the cancer coagulome found expression of genes encoding six pro‐coagulant and fibrinolytic factors (F3, PLAU, PLAT, PLAUR, SERPINB2, and SERPINE1) in The Cancer Genome Atlas, and correlated with VTE incidence in 32 cancer types in a previously reported Dutch study." (PMID 37147936, 2023). "Moreover, the upregulated expression of SOD2, IL1B, PLAUR, CXCL3, and CCL20 promoting cancer cell invasion in other tumors depended on the NF-κB mechanism." (PMID 37954130, 2023). "Further analysis of TAM-stimulated primary cancer cell clusters compared to naïve cell clusters revealed that c-Myc, PLAU, PLAUR, and AXL were significantly upregulated, while the downregulated epithelial marker (EPCAM) was observed in the disseminated cell clusters." (PMID 35680853, 2022).
cancer (continued). "On the other hand, PLAUR and MRC2 are involved in the activation of plasminogen and, although the benefit of targeting these proteins in fibrosis remains to be fully demonstrated, encouraging results have been reported for cancer settings." (PMID 36531712, 2022). "As the expression level of the PLAUR gene in pan-cancer has not yet been precisely determined, we utilized TCGA and GTEx databases for the differential expression analysis of PLAUR mRNA in the 20 most prevalent types of human cancer." (PMID 36052236, 2022). "Reports suggest that non-proteolytic activity of PLAUR is more essential for cancer progression than promotion of cell invasion." (PMID 27685627, 2016). "Significant upregulation of expression of 3 target genes (MMP9, PLAUR and SERPINE1) of miR-204 had been observed in cancer tissues as expected since it is known that downregulated expression of miRNAs may upregulate expression of target genes." (PMID 27597234, 2016). "Recent reports shed light on PLAU/PLAUR roles that are not directly related to cell migration; thus, PLAUR affects epithelial-to-mesenchymal transition, stemness properties of cancer cells, metabolic state of cancer cells." (PMID 29254187, 2017). "However, inhibition of proteolytic function of PLAUR was not efficient in clinical trials, strengthening the importance of proteolysis-independent functions of PLAUR in cancer." (PMID 27685627, 2016). "However, at least three genes induced in the fibroblast serum response, PLAUR, LOXL2, and MIF, have been previously shown to increase cancer invasiveness or angiogenesis in animal xenograft models; each of these three genes has also been shown to play an important role in wound healing." (PMID 14737219, 2004).
infection (38 papers, 2008 to 2025). The state of being infected such as from the introduction of a foreign agent such as serum, vaccine, antigenic substance or organism. "Correlations between PRRs and transcripts related to thrombosis and coagulation identified three transcripts having the highest associations with PRRs across all three infections: PLAUR, SERPING1, and SELPLG." (PMID 40825056, 2025). "Common associations were observed across all three infections which most frequently involved PLAUR and SERPING1, suggesting that common pathways linking acute respiratory infection to thrombosis may involve these gene transcripts." (PMID 40825056, 2025). "The gene transcripts with the greatest number of shared correlations with PRRs across all three infections were PLAUR (with TLR2, RIG-I, LGP2) and SERPING1 (with TLR5, RIG-I, MDA5, and LGP2)." (PMID 40825056, 2025). "Two additional features were found in the CPS301 signature and in the ISAv dataset: PLAUR and Slime mold cyclic AMP receptor, both being included in CPS301 as their expression suggested an involvement in a response to IHNv and ISAv-infection." (PMID 28702195, 2017).
kidney disease (13 papers, 2014 to 2026). "However, the relevance of this murine isoform 2, or any other PLAUR-encoded isoforms, to human kidney diseases remains to be determined." (PMID 41480757, 2026). "Associated variants were found in and around genes encoding uPAR (PLAUR), its ligand uPA (PLAU), the kidney-disease-associated gene PLA2R1 as well as genes with relations to glycosylation, glycoprotein biosynthesis, and the immune response." (PMID 34079037, 2021).
cardiovascular disease (10 papers, 2009 to 2025). "In conclusion, we believe PLAUR is a reliable target for future cardiovascular disease therapy, although more research is needed to demonstrate PLAUR’s unique molecular mechanism of action." (PMID 37810795, 2023). "While we have not formally tested the association between PLAUR SNPs and cardiovascular disease outcomes as we do not have this information, this seems unlikely." (PMID 19878584, 2009).
inflammation (8 papers, 2009 to 2026). Aberrant reaction of the microcirculation characterized by movement of fluid and leukocytes from the blood into extravascular tissues. "Although PLAUR has an important fibrinolytic role similar to that of tPA, this molecule plays a key role in inflammation, cell adhesion, and chemotaxis; pre-clinical data demonstrated that decreased levels of PLAUR are correlated to decreased lung inflammation." (PMID 40243422, 2025).
PLAUR also shares sentences with these, for which no sentence is quoted: small cell lung carcinoma (13 papers); acute myeloid leukemia (11); squamous carcinoma (11); triple-negative breast carcinoma (11); lymph node metastasis (10); viral infection (10); head and neck cancer (9); head and neck squamous cell carcinoma (9); oral cancer (9); endothelial dysfunction (8); hematologic malignancies (8); malaria (8); multiple myeloma (8); neurological diseases (8); pancreatic adenocarcinoma (8); renal fibrosis (8); colitis (7); diabetic kidney disease (6); esophageal squamous cell carcinoma (6); focal segmental glomerulosclerosis (6); infectious disease (6); acute kidney injury (5); adenocarcinoma (5); Alzheimer disease (5); bacterial infection (5); cerebral malaria (5); fibrosarcoma (5); gastric adenocarcinoma (5); heart failure (5); ischemic stroke (5).
A further 230 diseases each share a sentence with PLAUR in 5 papers or fewer.